Y_RNA (Y RNA )
Gene: Miscellaneous RNA gene on chromosome 15 (66,348,276 to 66,348,375, forward strand). Ensembl gene ENSG00000223271.
Homologues: Orthologues: chimpanzee Y_RNA (94% identical), macaque Y_RNA (84% identical). Paralogues in human: Y_RNA (89% identical), RNY1 (84% identical), Y_RNA (84% identical), Y_RNA (83% identical), Y_RNA (82% identical), RNY1P11 (81% identical), Y_RNA (81% identical), Y_RNA (80% identical), Y_RNA (79% identical), RNY1P10 (78% identical), Y_RNA (78% identical), RNY1P8 (77% identical), and 95 more.